BCL2 (BCL2 apoptosis regulator)
Diseases named in the same sentence as BCL2 in open-access papers (continued):
Sharing a sentence is not in itself a finding about the gene and the disease.
viral infection (continued). "Two key proteins, Bax and Bcl-2, involved in the regulation of apoptosis, were analyzed using the RT-qPCR method; the results showed that recombinant virus infection upregulated Bax and downregulated Bcl-2 in B16F10 cells, indicating an increased propensity for apoptosis." (PMID 39458338, 2024). "Data from several studies in bat cells suggest that heightened IFN responses in these cultures may prolong viral infection by limiting pathogen-induced cell death through induction of anti-apoptotic genes including BCL-2 and PMAIP139,80." (PMID 37898615, 2023). "Overall, BCL-2 proteins present a target that could be exploited in some viral infections and BCL-2 inhibitors could further expand to be used as antivirals." (PMID 36569952, 2022). "Thus, the development of inhibitors of BCL-2 proteins has been of great interest for the virus infection and cancer fields." (PMID 36569952, 2022). "Furthermore, BHRF1 has 38% sequence homology with the antiapoptotic protein Bcl-2 and the function of BHLF is also similar to that of Bcl-2, leading to persistent virus infection and contributing to tumourigenesis." (PMID 34034760, 2021). "The comparable transcript levels of CXCL10, CCL2, and BCL2, as well as viral loads were observed between control and rIL-22-treated groups, indicating that IL-22 was dispensable for the growth, activation, and viral infection of human glial cells." (PMID 32843067, 2020). "The B-cell lymphoma 2 (Bcl-2) proteins family is the main arbiter of mitochondrially mediated apoptosis, and viruses have evolved sequence and structural mimics of Bcl-2 to subvert premature host cell apoptosis in response to viral infection." (PMID 29053589, 2017). "Thus, a specific structural feature and molecular mechanism of the v-Bcl-2 that is shared with host antiapoptotic Bcl-2 proteins is important for the function of this protein during viral infection." (PMID 16201011, 2005). "BCL2 (ΔH = −0.0405) functions as a key anti-apoptotic regulator, potentially contributing to the fine-tuning of cell death during antiviral responses—an adaptation that may help bats limit immunopathology while tolerating persistent viral infections." (PMID 41227394, 2025). "Moreover, several studies have described its potential to modulate Bcl-2 expression, which has an essential role in regulating several cellular processes that could have an impact on viral infection progression." (PMID 35130828, 2022). "BCL-2 inhibitors have the potential to hinder viremia in viral infections where BCL-2 anti-apoptotic proteins are upregulated, but when these anti-apoptotic proteins are downregulated a BCL-2 inhibitor could aid infection and have drastic effects on a patient’s health." (PMID 36569952, 2022). "Similarly, treatment with pan-Bcl-2 or Bcl-xL-specific inhibitors could be harmful for patients with viral diseases (similarly to mice)." (PMID 32630560, 2020). "Therefore, we speculated that virus infection alters the expression of BCL2 proteins through the induction of cellular stress." (PMID 30261081, 2018). "Our study showed that viral infection activated STAT5B phosphorylation, accelerated BCL2 consumption and triggered subsequent apoptosis response." (PMID 36928081, 2023). "This review examines potential routes for BCL-2 and Jak 1/2 inhibitors as immunomodulators for treatment and cure of HIV-1 and other viral infections." (PMID 36569952, 2022). "DAPK1 induces a type of noncanonical autophagy, which is induced by the upregulation of DAPK1 expression induced via viral infection, and DAPK1 directly phosphorylates Beclin1, thereby releasing it from Bcl-2." (PMID 36170016, 2022). "The ability of Wt1-5 infection to induce the expression of caspases 3 and 8 and pro-apoptotic proteins BAX, Bcl2, and BID suggest that virus infection, at least at late stages of the viral life cycle, leads to apoptotic cell death." (PMID 32722005, 2020).
viral infection (continued). "Failure to suppress protein misfolding in persistently stressed cells, such as during a viral infection, can then result in activation of the proapoptotic transcription factor CHOP, leading to suppression of the antiapoptotic protein B cell lymphoma-2 (Bcl-2)." (PMID 26792742, 2016). "It is interesting to point out that Bcl-2 is an important anti-apoptotic factor and, like Bcl2A1, helps KSHV infection bypass apoptosis, an important barrier inherent in virus infection, as well as autophagy, a pathway well-known to antagonize KSHV infection." (PMID 25340789, 2014). "Higher expression of B–cell markers CD19, CD20 in CLL with viral infection suggests a change to atypical CLL, sustained by elevated expression of known poor prognosis markers bcl–2, cyclin D1 and CD38." (PMID 22567048, 2011). "Additionally, DEGs related to the response to viral infections, such as DDIT4, CXCR4, EIF5A, TNFAIP3, BCL2, and IRF1, were also upregulated in NBs." (PMID 38440735, 2024). "In Vero cells, BCL-2 expression prevents apoptosis but does not affect viral infection, replication, or release which indicates that although SARS-CoV causes apoptosis, it is not necessary for viral dissemination." (PMID 36569952, 2022). "Treatment plans should consider co-infections and viral infections in individuals with cancer before incorporating BCL-2 inhibitors so as not to further impair a patient’s health." (PMID 36569952, 2022). "Notably, in the context of MCMV viral infection, a novel IFN-I dependent mechanism has been identified by which NK cells evade mechanisms of cell death via BCL2 signaling." (PMID 34721400, 2021). "Autoreactive clones because of genetic abnormality (BCL-2, C-MYC) are activated by viral infections and other unknown events." (PMID 31873137, 2019). "During viral infection, Ks-Bcl-2 appears to play a pivotal role in completion of the lytic cycle, as a Ks-Bcl-2 deletion virus of KSHV does not complete the lytic replication cycle." (PMID 28984827, 2017). "During cellular stress condition such as exposure to cytotoxic drugs, ultraviolet (UV) irradiation or viral infection, BH3-only proteins expression is up-regulated, resulting in the activation of Bak and Bax and/or neutralization of the pro-survival Bcl-2 proteins." (PMID 29053589, 2017). "We found an increased value in CD38, bcl–2 and cyclin D1 markers in patients with viral infection, but unfortunately without statistical significance (p>0.05)." (PMID 22567048, 2011). "However, in the context of viral infections, particularly HIV and by extension potentially HTLV-1, the strategy of BCL-2 inhibition may be more effective because viral persistence often relies heavily on BCL-2-mediated survival of infected cells." (PMID 41201565, 2025). "No alteration in the transcriptional expression of BCL2 was detected upon viral infection." (PMID 36456548, 2022). "Thus, the strong up-regulation of HRK but not Bcl-2 as well as the minor Bcl-xL up-regulation provides evidence that the viral infection was able to trigger apoptosis." (PMID 22238639, 2012). "In addition, no obvious effect on protein level accumulation of BCL2 was detected after treating nonviruliferous SBPH with dsSOCS5 compared with the control (lanes 1 vs. 2), suggesting that SOCS5 imposes a negative effect on BCL2 accumulation during viral infection." (PMID 36928081, 2023). "Our results indicate that systemic treatment with combinations including pan-Bcl-2 or Bcl-xL-specific inhibitors (e.g., ABT-263 and A-1155463) could be harmful for cancer patients (similarly to round worms), because patients are constantly exposed to radiation, chemicals, and viral infections." (PMID 32630560, 2020).
Alzheimer disease (59 papers, 2013 to 2025). A progressive, neurodegenerative disease characterized by loss of function and death of nerve cells in several areas of the brain leading to loss of cognitive function such as memory and language. "Out of the three hubs, one hub (BCL2) was already found to be related to Alzheimer’s Disease, which was further studied for their association in human PD." (PMID 29653596, 2018). "Considering these ratios, the Alzheimer’s disease network associates were as a group more oncogenic than the associates of BCL-2, considered to be a benchmark oncogene and this result is counterintuitive, considering the degenerative character of the disease." (PMID 24196233, 2013). "Of note, the detected lowering in Bcl2 immunostaining area % could be due to neuronal loss; shrinkage of the neuronal soma, which has been reported as a common pathological outcome in Alzheimer’s disease; or both." (PMID 37630980, 2023). "The Bcl‐2 downregulation is closely related to mitochondrial abnormalities, apoptosis, and Alzheimer's disease." (PMID 39912396, 2025). "In Alzheimer’s disease, amyloid beta drives increased expression of miR-16-5p, which induces apoptosis through downregulation of Bcl-2." (PMID 38445373, 2024). "The hub gene, PTSG2, is related to the NF-κB and Alzheimer’s disease pathways, whereas RELA and BCL2 are associated with the NF-κB pathway." (PMID 37719850, 2023). "Human studies showed the upregulation of the BCL2 expression in the brains of AD (Alzheimer’s disease) patients." (PMID 36324052, 2023). "TDN injection in Alzheimer's disease rats significantly reversed these changes, restoring the expression of active caspase‐3, Bax and Bcl‐2 to the levels of the control and sham groups (P < .01)." (PMID 32162733, 2020). "The upregulation of Bcl-2 with DNA damage was found in Alzheimer’s disease, possibly as a protective mechanism." (PMID 33336032, 2020). "In contrast, both the protein and mRNA expression levels of active caspase‐3 and Bax were significantly higher in the Alzheimer's disease than in the control group and sham groups, while Bcl‐2 expression levels were significantly lower (P < .01)." (PMID 32162733, 2020). "Among the other screened hub proteins, ENO1, is reportedly involved in aging and age-related diseases, such as Alzheimer’s disease, while BCL2, belongs to an anti-apoptotic protein family." (PMID 29907735, 2018). "Bim levels are also decreased in the brain of Alzheimer’s disease patients and Bcl-2 is protective against Alzheimer’s disease-related insults." (PMID 29631601, 2018). "Similar studies employing neuronal cells modelling protein aggregation typical of Alzheimer’s disease have also reported a significant reduction in apoptotic cell death when these cells overexpressed anti-apoptotic Bcl-2." (PMID 28109286, 2017). "Bcl-2 expression in the brain is up-regulated in Parkinson disease and Alzheimer disease, with Bcl-2 expression increasing with increased disease severity." (PMID 23437205, 2013). "Analysis of post-mortem brain samples from patients with Alzheimer disease showed that the level of Bcl-2 expression were significantly higher in the cerebellum than in the frontal lobe." (PMID 23437205, 2013). "Similarly, another study reported that Lut treatment increased Bcl-2 expression while reducing levels of pro-apoptotic proteins, such as Bax, Cyt c, cleaved Caspase-3, and cleaved Caspase-9 in a model of Alzheimer’s disease-induced neuronal apoptosis." (PMID 40332364, 2025). "The modulation of pathways involving PI3K, Trk-A, Trk-B, Bcl2, GSK3βser9, and Erk1/2 underscores FVSEs potential role in promoting neuronal survival and function, especially in managing neurodegenerative conditions like Alzheimer’s disease." (PMID 39684414, 2024).
Alzheimer disease (continued). "FVSEs impact on key signaling components like Bcl2 and GSK3βser9 supports synaptic stability and axonal growth, mechanisms essential for preserving cognitive function and resilience in neurodegenerative diseases (NDs) like Alzheimer’s disease." (PMID 39684414, 2024). "Formerly, it was reported that the anti-apoptosis effect of BBR in Parkinson's disease (PD) and Alzheimer's disease (AD) might take place through the restoration of Bcl-2/Bax and Bcl-xl/Bax, and our findings were in accordance with theirs." (PMID 36017075, 2022). "In Alzheimer’s disease (AD) cell model, DPSCs’ secretome reduced the amyloid beta (Aβ) peptide-mediated cell cytotoxicity and apoptosis by stimulating the endogenous survival factor Bcl-2 and decreasing the apoptotic regulator Bax." (PMID 34712658, 2021). "Moreover, PaPE-1 normalized the Aβ-induced loss of mitochondrial membrane potential and restored the BAX/BCL2 ratio, suggesting that the anti-Alzheimer’s disease (AD) capacity of PaPE-1 particularly relies on inhibition of the mitochondrial apoptotic pathway." (PMID 34797527, 2021). "The results of this experiment showed that apoptotic neurons increased, Bcl-2 decreased and Bax increased, in the cortex and hippocampus of AD model mice, indicating that Alzheimer's disease brain has a pro-apoptotic effect on tissues, and rTMS has an anti-apoptotic effect." (PMID 34965216, 2021). "Moreover, it could up-regulate the cerebral levels of B-cell lymphoma 2 (Bcl-2) as a neurotrophic factor in Alzheimer’s disease transgenic mice." (PMID 37605729, 2023). "In addition, overexpression of miR-137 enhances viability and suppresses apoptosis of neuronal cells, decreases cleaved caspase 3 levels and increases Bcl-2 protein levels in a cell model of Alzheimer's disease, highlighting its neuronal protective effects, which was in accordance with our findings." (PMID 32496209, 2020). "In the present study, we found that FMJ can ameliorate the spatial memory impairment through apoptotic signaling pathway, which could increase the expression of Bcl-2 and downregulate the expression of Bax and caspase-3 in the hippocampus of rats with Aβ1–40-induced Alzheimer's disease." (PMID 25050129, 2014). "The mitochondrial dynamics and mitophagy are also impaired during thedevelopment of Alzheimer’s disease.This is evidenced by alterations in the expression of the ATG5, Beclin1, LC3A,LC3B, PINK1, TERT, BCL2, and BNIP3L genes detected in a mouse model of AD." (PMID 41479568, 2025). "Roflumilast, in an Alzheimer’s disease (AD) model using APP/PS1 double transgenic mice, showed reduced neuronal death, increased cAMP/CREB/BDNF signaling, and improved Bcl-2/Bax ratios." (PMID 39851514, 2025). "Further, BCL2 and its interaction with BECN1 regulate the clearance of amyloid β oligomers that contribute to a mouse model of Alzheimer’s disease, and impact mouse lifespan." (PMID 39602254, 2024). "In Aβ1–40-induced Alzheimer’s disease (AD), ginsenoside Rb1 inhibits the expression of BAX and caspase-3 in the hippocampus and increases the expression of BCl-2, thereby regulating the neuronal cell death pathway and preventing AD." (PMID 37686071, 2023). "To study how autophagy physiologically regulates the progression of Alzheimer’s disease (AD), we generated a new knock-in mouse model with hyperactive autophagy, by genetically disrupting the nutrient-regulated interaction between BECN1 and its inhibitor BCL2." (PMID 28806762, 2017). "Similarly, in an Alzheimer’s disease (AD) model where SH-SY5Y cells were exposed to Aβ, semaglutide inhibited apoptosis by downregulating the expression of Bax induced by Aβ and upregulating the expression of Bcl2 suppressed by Aβ." (PMID 38002034, 2023).
esophageal cancer (59 papers, 1999 to 2026). A primary or metastatic malignant neoplasm involving the esophagus. "The polymorphisms of Bcl-2 were significantly associated with the risk of developing esophageal cancer." (PMID 38464761, 2024). "As we all know, the expression of BCL-2 is believed to be antiapoptotic and causes drug resistance in many cancer species, including esophageal cancer." (PMID 39165489, 2024). "They found that the BCL-2 rs2279115 AA genotype was significantly associated with increased risk of developing esophageal cancer." (PMID 26132559, 2015). "Therefore, the Stat3/Bcl-2 pathway-mediated apoptosis underlies the cell-type-specific drug sensitivity, suggesting metformin possesses a therapeutic activity and selectivity on esophageal cancer." (PMID 32258099, 2020). "In another study, introducing BCL2 inhibitors into chemotherapy achieves favorable effects in patients with esophageal cancer, suggesting their potential to be widely used in solid tumor treatments." (PMID 39735667, 2025). "Our results indicate that Ori can reduce Bcl-2 mRNA levels and increase Bax mRNA levels in esophageal tissue of mice with esophageal cancer, suggesting that Ori can promote tumor cell apoptosis by inhibiting NLRP3 inflammasome activation." (PMID 40606986, 2025). "In esophageal cancer, zerumbone-triggered downregulation of Bcl-2 expression has also been proven to be responsible for induction of apoptosis." (PMID 35931788, 2023). "Some studies have shown that the upregulation of Bax/Bcl2 ratio promoted apoptosis in esophageal cancer as well as prostate, bladder, and renal cancer cells." (PMID 37110586, 2023). "Esophageal Cancer: curcumin modulated Notch-1 signaling and suppressed NF-jB and its downstream targets involving Bcl2, cyclin D1, VEGF, and MMP-9 in oral squamous cell carcinomas." (PMID 36712505, 2022). "Treatment with 400 μmol/l NaHS (an H2S donor) for 24 h markedly reduces apoptosis, as indicated by the decreased levels of cleaved caspase-3 and Bax and increased Bcl-2 expression in human esophageal carcinoma EC109 cells." (PMID 35795862, 2022). "MiR-296 has been found to contribute to 5-FU resistance in esophageal cancer cells through modulating the expression of P-gp, Bcl-2, Bax, cyclin D1 and P27." (PMID 34881242, 2021). "Here, genistein up-regulated Bax and Bid levels, while down-regulating Bcl-2 and Bcl-xl expression, suggesting that the effects of genistein against esophageal cancer are multifaceted." (PMID 32276266, 2020). "Up-regulation of RACK1 confers resistance to radiation in esophageal cancer partially through up-regulating BCL2." (PMID 30537994, 2018). "Finally, when only looking at models with SNPs + methylation + TFs included, we found the predictive gain from miRNA in esophageal cancer strengthening, suggesting the effect of miRNA on BCL2 expression in esophageal cancer is conditioned on BCL2’s cis-SNPs." (PMID 40041206, 2025). "In esophageal cancer, it inhibits tumor growth by regulating apoptosis and the NF-κB signaling pathway, increasing radiosensitivity, increasing the expression of cleaved caspase 3 and Bax, and decreasing Bcl-2 and NF-κB levels in vitro." (PMID 38248336, 2024). "Here, we conducted a retrospective study on the histopathology of ESCC, investigated the expression of Beclin-1 and Bcl-2 proteins (both autophagy- and apoptosis-related) in esophageal cancer tissue, and analyzed the significance of these proteins for the prognosis of ESCC." (PMID 34257544, 2021). "It has been found that miR-27a could increase the expression of P-gp and Bcl-2, as well as reduce Bax expression in esophageal cancer cells." (PMID 34881242, 2021).